CASP1 (caspase 1)
Diseases named in the same sentence as CASP1 in open-access papers (continued):
Sharing a sentence is not in itself a finding about the gene and the disease.
colorectal cancer (continued). "To investigate whether NEAT1 promotes the progression of colorectal cancer by promoting an inflammatory response, we applied qRT-PCR, Western blot, and IHC assay, which showed that the expression of IL1B and caspase-1 increased in tumor tissues and cancer cells." (PMID 36213831, 2022). "In addition, mice lacking ASC and caspase-1 are also prone to DSS-induced colitis and colon-related colorectal cancer, which provides a great deal of evidence for the protective role of inflammasome in colorectal cancer inflammatory models." (PMID 33776057, 2021).
ischemia (30 papers, 2013 to 2025). A hypoperfusion of the BLOOD through an organ or tissue caused by a PATHOLOGIC CONSTRICTION or obstruction of its BLOOD VESSELS, or an absence of BLOOD CIRCULATION. "Administering VX-765 to open-chest rats at reperfusion is just as protective as administering VX-765 prior to ischemia, indicating that caspase-1 (and/or 4) causes all of its injury during reperfusion." (PMID 36835212, 2023). "Taken together, inhibition of caspase-1 significantly ameliorates ischemia-associated BBB injury and integrity by suppressing the activation of pyroptosis as well as the RAGE/MAPK pathway." (PMID 33584203, 2020). "ASC-deficiency in a partial liver ischemia showed an inhibition in the caspase 1/IL-1β signaling and protection against liver IRI." (PMID 33114395, 2020). "However, the mechanism underlying the observed dependence for caspase-1/11 signaling in mitochondrial respiration during ischemia is unknown, and further studies to separate the contribution of caspase-1 and -11 to this process are required." (PMID 33546173, 2021). "However, the role of caspase-1/11 in the recovery of muscle from ischemia caused by peripheral arterial disease is unknown." (PMID 32641037, 2020). "To study the relationship between caspase-1/4 and reperfusion injury, we measured infarct size (IS) in isolated mouse hearts undergoing 50 min global ischemia/2 h reperfusion." (PMID 36835212, 2023). "NaHS use reduced the pyroptosis of retinal cells and brain neurons through inhibition of the NLRP3/caspase-1/GSDMD signaling pathway in an ischemia/reperfusion injury model." (PMID 37445920, 2023). "It is reported that H2S can reduce neuronal inflammation by inhibiting the NLRP3/caspase-1/GSDMD signaling pathway in ischemia/reperfusion brain injury." (PMID 37445920, 2023). "Although the expression of caspase-1/11 and IL-1β/IL-18 is controversial due to the differences in subjects and the time of ischemia, consistent with our study, the expression of GSDMD and GSDMD-N increased during myocardial ischemia." (PMID 35783187, 2022). "So, we used immunohistochemistry to detect NLRP3, Caspase-1 and IL-1β levels in the right striatum of ischemia region." (PMID 33461169, 2021). "The mechanism research showed that the levels of NLRP3, caspase-1, IL-1β and IL-18 were all increased in rat brain with I/R injury, which was ischemia for 1 h and then reperfusion for 24 h." (PMID 34445481, 2021). "Full-length and cleaved caspase-1 were detected immunohistochemically in TA myofibers from mice at 21 days after induced ischemia or normally perfused controls." (PMID 32641037, 2020). "Herein, caspase-1 inhibitor vx-765 protected peri-infarct region against hypoxia damage and ameliorated neurological dysfunction after ischemia." (PMID 33584203, 2020). "In mouse models of familial amyotrophic lateral sclerosis and ischemia-induced brain injury, caspase-1 is reported to be involved in the disease pathogenesis, tBid generation, and caspase-3 activation in the spinal cord and the brain, respectively." (PMID 31064994, 2019). "Inhibition of HMGB1 significantly suppressed the expression of NLRP3, ASC, and the maturation of caspase-1 in ischemia retinal tissue." (PMID 26224068, 2015). "Active IL-18 requires cleavage of its precursor form by caspase-1; inhibition of caspase-1 also attenuated the depression in contractile force after ischemia (from 35% of control to 75.8% in treated atrial muscle)." (PMID 24115947, 2013). "Consequently, pharmacologic inhibition of caspase-1 using vx-765 ameliorated ischemia-induced infarction, neurological deficits, and neuronal injury." (PMID 33584203, 2020). "Besides, accumulating studies of cerebral stroke, ischemia, or hemorrhagic have reported that the selective inhibitor of caspase-1, AC-YVAD-CMK, was proved to have a therapeutic effect and pyroptosis was involved in the pathophysiological process." (PMID 31814872, 2019).
ischemia (continued). "Furthermore, the neurologic score was consistent with the mRNA transcription levels of NLRP3, IL-1β, and caspase-1 in the ischemia core." (PMID 29853850, 2018). "Taken together, blockade of caspase-1 may represent an intriguing way to alleviate inflammatory responses to focal ischemia." (PMID 23935248, 2013). "Nevertheless, our findings overlap but are distinct from a previous study, which demonstrated that RLX could attenuate caspase-1 activity in an in vivo model of ischemia/reperfusion injury via an eNOS-dependent mechanism, in which the direct involvement of the NLRP3 inflammasome was not provided." (PMID 32848798, 2020). "This led to a greater increase in TLR4, P2X7, IκBα activation, NLRP3, ASC, cleaved caspase-1, and pro-inflammatory cytokine IL-1β levels in the Stress+ISCH group compared to the ischemia-alone group." (PMID 32466385, 2020). "Moreover, endogenous IL-18 is induced by IL-1β via caspase-1 under ischemic conditions in human myocardial tissue and that inhibition of caspase-1 reduces the processing of endogenous precursors of IL-18 and IL-1β and thereby prevents ischemia-induced myocardial dysfunction." (PMID 24115947, 2013). "Western blot results showed that not only the expression of pyroptosis-related proteins such as NLRP3 and cleaved caspase-1 was increased in the retinal neurons with ischemia/reperfusion injury in vivo and in vitro, but also the expression of NLRP3 and cleaved caspase-1 was increased." (PMID 40236697, 2025). "In a mouse ischemia/reperfusion model, hypoxic preconditioning decreased pyroptosis to prevent inflammatory injury by inhibiting the expression of the NLRP3 inflammasome and the related proteins Caspase-1 and Gasdermin D." (PMID 38317957, 2024). "During ischemia, the produced DAMPS activate inflammasomes, which generate caspase-1." (PMID 35624707, 2022). "Absence of caspase-1/11 resulted in significantly diminished maximal and spare respiratory capacity compared to WT regardless of ischemia or CQ treatment." (PMID 32641037, 2020). "Furthermore, as the second control experiment, interruption of blood flow to induce ischemia only without subsequent reperfusion did not lead to activation of caspase 1, which was correlated well with our earlier findings in the data mining analysis." (PMID 33114395, 2020).
Parkinson disease (30 papers, 2008 to 2026). A progressive degenerative disorder of the central nervous system characterized by loss of dopamine producing neurons in the substantia nigra and the presence of Lewy bodies in the substantia nigra and locus coeruleus. "Patients with Parkinson’s disease (PD) have increased levels of inflammasome-associated proteins, including IL-1β and caspase-1 that can cause neuroinflammation and subsequent damage to dopaminergic neurons." (PMID 37443800, 2023). "For instance, in models of Alzheimer's and Parkinson's diseases, pathological proteins such as β-amyloid and α-synuclein can activate inflammasomes and trigger the caspase-1/GSDMD pathway, ultimately resulting in neuronal death." (PMID 41563626, 2026). "QijiShujiang granules alleviate the dopaminergic neuronal injury of Parkinson’s disease by inhibiting the NLRP3/caspase-1 pathway." (PMID 40305201, 2025). "In post mortem studies of brains from Parkinson’s or Alzheimer’s patients, overexpression of IL1β and Casp1 was reported." (PMID 39330566, 2024). "BA results in the remission of neuroinflammation through limiting the NLRP3/caspase-1/GSDMD pathway in mice with Parkinson's disease." (PMID 39662962, 2024). "NLRP3/caspase-1/GSDMD pathway was shown to contribute to neuroinflammation in mouse model of Parkinson’s disease induced by N-methyl-4-phenyl-1,2,3,6-tetrahydropyridine (MPTP)." (PMID 39253076, 2024). "In a TLR4-dependent manner, MPTP activated NLRP3/caspase-1/GSDMD cascade in mouse model of Parkinson’s disease." (PMID 39253076, 2024). "Owing to the dual effect of Parkinson’s disease and surgical trauma, Aβ accumulation can activate NLRP3 and upregulate the expression levels of IL-1β, IL-18, and Caspase-1 to cause inflammation." (PMID 37232753, 2023). "In a model of human vascular endothelial cells, CLZ decreased ASC and caspase-1, while in renal I/R, it suppressed caspase-1, and in Parkinson-diseased rats, it reduced IL-1β." (PMID 36127628, 2022). "The serum levels of alpha-synuclein (α-synuclein) and caspase-1 are lower in Parkinson’s disease (PD) patients than in healthy individuals." (PMID 33584697, 2020). "The study has investigated the effect of isoflavone attenuates the caspase-1 and caspase-3 level in cell model of Parkinsonism." (PMID 26161002, 2015). "If (Casp1, Ifngr, Nos2)−/− mice indeed have increased levels of dopamine and/or glutamate, they might prove useful as pre-clinical models of Parkinson’s disease." (PMID 31015500, 2019). "In this study, we observed the influence of isoflavone on cell model of Parkinsonism and how the caspase-1 and caspase-3 play a role in the course of injury induced by MPP+ in PC12 cells, in order to explore the protective mechanism of isoflavone to Parkinson's disease." (PMID 26161002, 2015). "In Parkinson’s disease, MCC950 treatment significantly decreased the NLRP3 and caspase-1 in the substantia nigra of the brain and elevated the level of the dopamine metabolite 3,4-Dihydroxyphenylacetic acid." (PMID 40906404, 2025). "In an animal model of Parkinson's disease, treatment with CBD reduced NLRP3 and caspase 1 levels, as well as improvements in neurological impairment." (PMID 40245261, 2025). "Key signaling pathways involved in inflammasome activation in microglial cells during Parkinson’s disease progression include TLRs/NF-κB/NLRP3, TLR/NLRP3/Caspase-1, and NF-κB/AP-1/Nrf2." (PMID 40552323, 2025). "In mouse models of Parkinson’s disease, the downregulation of miR-30e, miR-190, and miR-7 enables NLRP3 and ASC expression, the cleavage of caspase-1, the release of IL-1β and IL-18 cytokines, and the cell death by pyroptosis." (PMID 34829842, 2021). "The identification of CASP1 and HTRA2, a mitochondrial serine protease mediating apoptosis in Parkinson’s disease, also highlights the important role of caspase-dependent apoptosis in merlin-deficient Schwann cells in an in vitro model of NF2." (PMID 32848608, 2020).
Parkinson disease (continued). "Injections of the caspase-1 inhibitor, Ac-YVAD-CMK, into the brains of two rat models of Parkinson’s disease (LPS-induced and 6-OHDA induced) reduced neurodegeneration of dopaminergic neurons in the substantia nigra and reduced the expression of inflammasome components." (PMID 35185469, 2022). "Exogenous administration of several miRNAs (miR-30e, miR-190, miR-7) to Parkinson’s disease mice models inhibits NLRP3, ASC, and caspase-1 expression, impairing the release of IL-1β and IL-18, limiting pyroptosis and, consequently, neuroinflammation and neuronal damage." (PMID 34829842, 2021). "Moreover, various components of the NLRP3 inflammasome, such as Caspase-1, NLRP3 and ASC, are markedly upregulated in microglia within the substantia nigra of Parkinson’s disease patients, suggesting a link between pyroptosis and Parkinson’s disease." (PMID 39058145, 2024).
colon carcinoma (29 papers, 2013 to 2025). "Mice with the deficient NLRP gene and the caspase-1 gene are less likely to acquire colitis-related colon cancer." (PMID 35884370, 2022). "Recently, LXR was reported to induce caspase 1-dependent cell death in human colon cancer cell lines providing a mechanistic basis underlying some of the anticancer actions of LXR44." (PMID 27149934, 2016). "In conclusion, we have revealed that simvastatin induces pyroptosis through ROS/NLRP3/caspase-1/GSDMD pathway in colon cancer." (PMID 37974278, 2023). "Although previous study indicated the importance of caspase-3/GSDME pyroptosis pathway in colon cancer, our present study found simvastatin-mediated pyroptosis decreased in colon cancer cell when caspase-1 activity was inhibited by VX-765 incubation." (PMID 37974278, 2023). "This NLRP3/caspase-1/GSDMD pyroptosis pathway in response to simvastatin in colon cancer cells was consistent with the previsous study in non-small cell lung cancer." (PMID 37974278, 2023). "It was in integration suggested that simvastatin induced caspase-1-dependent pyroptosis in colon cancer cells." (PMID 37974278, 2023). "Inflammasomes have been reportedly activated by NLRP3-ASC-caspase-1, promoting the expression of the downstream factors IL-18 and IL-1β and playing an anti-tumor role in colon cancer." (PMID 35309942, 2022). "CLNA1 and CLNA2, two conjugated isomers of CLNA, can lead to pyroptosis by activating caspase-1 and caspase-4, 5 and induce colon cancer cell pyroptosis." (PMID 35884370, 2022). "Although there are many types of inflammasomes, NLRP3 inflammasomes are the most extensively studied and most complex caspase-1 inducers in intestinal inflammation and colon tumors." (PMID 34335248, 2021). "The IC50 of NWL vinyl sulfone small molecule caspase inhibitors were determined on Caspase-1 to 10, and Caspase-6-transfected human colon carcinoma HCT116 cells." (PMID 28241839, 2017). "A recent report showed that liver X receptor (LXR) ligands, such as TO901317 or 25-HC, promoted the caspase-1-dependent cell death of colon cancer cells." (PMID 27779191, 2016). "We have previously reported that LXR agonists induced colon cancer cell death in a caspase-1-dependent manner." (PMID 26450852, 2015). "In colon cancer, simvastatin induced pyroptosis via the caspase-1/GSDMD pathway." (PMID 40756987, 2025). "Then, we measured the activated caspase-1 in colon cancer cells by immunofluorescence staining." (PMID 37974278, 2023). "Taken together, our data suggested that AIM2 inhibits BRAF-mutant colon cancer growth in a caspase-1-dependent manner, which may provide evidence to understand the pathogenesis of CRC with BRAF-mutant, as well as new strategies for manipulation of CRC." (PMID 33842454, 2021). "However, during the malignant transformation, the ovarian and colon cancer cells lose the ability to process IL-18 as a result of the defective Caspase-1 activation." (PMID 34114949, 2021). "It is also a promoter of caspase-1 and can mediate colon cancer cell apoptosis." (PMID 25210949, 2014). "However, there are few studies on the role of CASP1 in colon cancer." (PMID 34026619, 2021). "Hu and colleagues studied caspase-1 mRNA expression levels in normal colon tissue and colon tumors from WT mice observing a significant reduction in caspase-1 mRNA expression levels in tumors compared to normal colonic tissue, suggesting that lack of caspase-1 may play a role in tumor progression." (PMID 23606794, 2013). "Our in vitro and in vivo results indicated that simvastatin induced pyroptosis through ROS/caspase-1/GSDMD pathway, thereby serving as a potential agent for colon cancer treatment." (PMID 37974278, 2023). "Recently, a study using an oxaliplatin resistance-related gene signature (consisting of CD22, CASP1, CISH, and ALCAM) to predict the survival of patients with colon cancer found that this gene signature has a better predictive value." (PMID 36145360, 2022).
colon carcinoma (continued). "Thereafter, we established a prognosis signature based on four genes [CD22, CASP1, CISH, and activated leukocyte cell adhesion molecule (ALCAM)] to evaluate the prognosis for colon cancer patients." (PMID 34026619, 2021). "Afterward, we established a model to predict the prognosis of colon cancer using four oxaliplatin resistance-related genes (ALCAM, CD22, CASP1, and CISH) on the basis of stepwise regression and LASSO Cox regression." (PMID 34026619, 2021). "However, it has been shown that Pycard(−/−), Casp1(−/−) mice and Nlrp3(−/−) mice are prone to inflammation associated colon cancer, suggesting that inflammasome activation or induction of pyroptosis restricts, rather than promotes, colon cancer development." (PMID 33941231, 2021). "Thirdly, there is little research on the role of CD22, CASP1, and CISH in colon cancer, even though it plays an important role." (PMID 34026619, 2021). "In addtion, the protein level of NLRP3, ASC, cleaved-caspase-1, mature IL-1β and GSDMD-N in isolated tumors significantly increased after simvastatin treatment, suggesting the induction of simvastatin on pyroptosis in colon cancer in vivo." (PMID 37974278, 2023). "Furthermore, the expression level of caspase-1 upstream proteins, NLPR3 and ASC was significantly increased after exposure to simvastatin in colon cancer cells." (PMID 37974278, 2023). "The risk scores calculated based on the expression levels and coefficients of four mRNAs (ALCAM, CD22, CASP1, and CISH) might be used to precisely and independently predict the prognosis of colon cancer." (PMID 34026619, 2021).